LINC00606 (long independently transcribed non-coding RNA 606)
Gene: Long non-coding RNA gene on chromosome 3 (10,759,350 to 10,764,307, reverse strand). Ensembl gene ENSG00000226567.
Diseases named in the same sentence as LINC00606 in open-access papers:
LINC00606 is named in the same sentence as 4 diseases in open-access papers, as found by Europe PMC text mining. Sharing a sentence is not in itself a finding about the gene and the disease. The quoted sentences say what the papers report.
glioblastoma (1 paper, 2024). The most malignant astrocytic tumor (WHO grade IV). "We substantiate for the first time that LINC00606 is considerably expressed in glioblastoma (GBM) patient specimens and is linked with adverse prognosis." (PMID 38725030, 2024). "LINC00606 regulates glioblastoma progression by sponging miR-486-3p and interacting with ATP11B." (PMID 38725030, 2024).
glioma (1 paper, 2024). A benign or malignant brain and spinal cord tumor that arises from glial cells (astrocytes, oligodendrocytes, ependymal cells). "Here, we show that LINC00606 expression is enriched in glioma, including GBM and LGG, and is associated with adverse prognosis, suggesting that LINC00606 can be used as a specific biomarker of glioma." (PMID 38725030, 2024). "Functionally, LINC00606 can promote the proliferation and migration of glioma cells and reduce the rate of apoptosis." (PMID 38725030, 2024). "This corroborates with our observations that downregulation of LINC00606 suppresses tumorigenesis of xenotransplanted glioma cells in vivo." (PMID 38725030, 2024). "In this study, we identified LINC00606 as a prognostic risk factor in GBM, which is highly expressed in glioma patients and is associated with a malignant prognosis." (PMID 38725030, 2024). "This will reveal in more detail that LINC00606, as a key node in the gene regulatory center network in gliomas, participates in the transcription factor-epigenetic regulator pathway and regulates tumor occurrence and development." (PMID 38725030, 2024). "With respect to the molecular mechanism, we found that LINC00606 mainly exists in the cytoplasm and promotes glioma progression by sponging miR-486-3p, which targets TCF12." (PMID 38725030, 2024). "We demonstrated that LINC00606 promotes glioma cell proliferation, clonal expansion and migration, while reducing apoptosis levels." (PMID 38725030, 2024). "This positive feedback loop mechanism expands our understanding of the epigenetic modification of LINC00606 in glioma." (PMID 38725030, 2024). "Therefore, understanding the underlying mechanisms of LINC00606 and/or ATP11B in glioma has novel implications in future therapies to inhibit glioma progression and recurrence." (PMID 38725030, 2024). "This suggests that LINC00606 may have the potential to regulate glioma genesis and progression, and that the biological functions and molecular mechanisms of LINC00606 in GBM remain largely unknown." (PMID 38725030, 2024). "In addition, the target gene TCF12 is highly expressed in glioma and acts as a transcription factor to control the transcription of LINC00606, PTEN, and KLLN." (PMID 38725030, 2024). "Our data provide insights into the regulatory mechanism of LINC00606 in glioma." (PMID 38725030, 2024). "Furthermore, the expression of 18F-FET in the brains of mice injected with ATP11B-overexpressing U251 cells was significantly reduced as compared with the vector, and OE ATP11B and sh-LINC00606 inhibited the growth of glioma cells in vivo model." (PMID 38725030, 2024). "LINC00606 was significantly upregulated in glioma tissue in comparison with normal brain tissue." (PMID 38725030, 2024). "In addition, knockdown of LINC00606 reduces the proliferation and migration of glioma cells and promotes apoptosis." (PMID 38725030, 2024). "Similarly, our in vivo results also show that decreased expression of LINC00606 inhibits tumor growth, indicating that LINC00606 may become a novel specific target for the treatment of glioma." (PMID 38725030, 2024). "The expression of LINC00606 and ATP11B in glioma and normal brain tissues was evaluated by qPCR, and the biological functions of the LINC00606/miR-486-3p/TCF12/ATP11B axis in GBM were verified through a series of in vitro and in vivo experiments." (PMID 38725030, 2024). "In conclusion, our findings provide important clues for further study of the molecular mechanism of LINC00606 and ATP11B in glioma." (PMID 38725030, 2024). "We elucidated the interaction between LINC00606 and ATP11B and the mechanism by which ATP11B, as an interacting protein, inhibits glioma cell proliferation, migration, and colony formation and increases the rate of apoptosis." (PMID 38725030, 2024). "Moreover, LINC00606 binds to ATP11B and participates in the regulation of the PI3K/AKT signaling pathway, which decreases the level of apoptosis and thus promotes the progression of glioma." (PMID 38725030, 2024).
cancer (1 paper, 2024). A tumor composed of atypical neoplastic, often pleomorphic cells that invade other tissues. "Moreover, according to analysis of The Cancer Genome Atlas (TCGA) and Genotype-Tissue Expression (GTEx) databases, LINC00606 is specifically highly expressed in GBM and LGG tissue, and almost completely absent in other cancers." (PMID 38725030, 2024).
tumor (1 paper, 2024). "RNA pull-down and mass spectrometry were performed to explore potential protein binding partners, and we screened 18 bindings proteins (unique peptide number > 8, PG coverage > 25%) as candidates for LINC00606 to exert tumor regulatory mechanisms in the GBM." (PMID 38725030, 2024). "Mechanistically, LINC00606 functions as a sponge for miR-486-3p to participate in the regulation of tumor malignant progression." (PMID 38725030, 2024). "Overall, the LINC00606/miR-486-3p/TCF12/ATP11B axis is involved in the regulation of GBM progression and plays a role in tumor regulation at transcriptional and post-transcriptional levels primarily through LINC00606 sponging miR-486-3p and targeted binding to ATP11B." (PMID 38725030, 2024). "In addition, the expression of ATP11B was negatively correlated with that of LINC00606 in GBM patient’s tumor samples." (PMID 38725030, 2024). "Furthermore, LINC00606 can bind to protein ATP11B, which exerts anti-tumor effects in GBM, and affects the apoptosis level of GBM through the PI3K/AKT signaling pathway axis." (PMID 38725030, 2024).